L1CAM (L1 cell adhesion molecule)
Diseases named in the same sentence as L1CAM in open-access papers (continued):
Sharing a sentence is not in itself a finding about the gene and the disease.
tumor (continued). "The expression of L1CAM mRNA was closely correlated with the tumor differentiation, depth of invasion, and tumor stage (P < 0.05 or P < 0.001), but was not significantly correlated with age, sex, lymph node metastasis, or other clinical parameters (data not shown)." (PMID 33710805, 2021). "L1CAM was detected on nerves in all tumor-negative tissues and in B cells in lymphatic follicles." (PMID 32545676, 2020). "EGFR, VEGF-A and L1CAM appeared to be unsuitable targets, as their high non-specific background staining in tumor-negative tissues could significantly affect the accurate visualization of tumor tissue during surgery." (PMID 32545676, 2020). "Furthermore, L1CAM+/CD133+ cells retained highest clonogenic capacity after irradiation and exhibited up-regulation of some CSC-specific genes, enhanced tumor-initiating capacity, self-renewal and higher tumor take rate in nude mice when compared with other cell populations." (PMID 31952346, 2020). "Future research will clarify if and to what extent L1CAM targeting represents a suitable strategy for innovative antitumor therapies, focusing in particular on the opportunity of defeating CSC-driven metastasis, relapse and drug resistance, thus contributing to tumor eradication." (PMID 32429448, 2020). "Thus, recent interesting findings that L1CAM, through PI3 and ERK, can promote cell surface sialyation and fucosylation in CHO cells and stem cells, despite the rapidly emerging relevance of the glycocalyx in tumor biology." (PMID 31455004, 2019). "While many aspects related to the pathobiology of L1CAM in the tumor vascular bed remain to be explored, this Ig-CAM may provide novel and alternative strategies in the context of vascular-targeting therapies in neoplastic diseases." (PMID 28134764, 2017). "Because the integrin α5β1 inhibitor ATN-161 can inhibit angiogenesis, we never exclude the possibility that ATN-161 administration might decrease the tumour growth of MDA-MB-231 cells and WT MEFs by inhibiting both L1CAM-mediated proliferation and angiogenesis." (PMID 28504692, 2017). "L1CAM-expressing VSCCs had a significantly worse prognosis compared to L1CAM-negative tumours." (PMID 27028855, 2016). "Moreover, we confirmed that spindle shaped epithelial tumour cells highly express L1CAM protein, in contrast to their cobble shaped counterparts, which show very low or absent L1CAM." (PMID 27028855, 2016). "None of the more differentiated or solid, keratinizing tumours showed any L1CAM positivity." (PMID 27028855, 2016). "Notably, the localization of L1CAM protein was detected mostly at tumor-adjacent stroma but not in the central area of the tumor." (PMID 25294816, 2014). "RNA was extracted from both L1CAM positive or negative tumor areas." (PMID 24497324, 2014). "L1CAM and EPCAM proteins could be useful markers to predict tumor progression and prognosis." (PMID 24422715, 2013). "Importantly, in none of the previous studies about the contribution of L1CAM to tumour progression, the specific roles of FL-L1CAM and SV-L1CAM have been distinguished." (PMID 21541352, 2011). "Our findings suggest that the L1CAM transcriptional regulation is more complex than anticipated and this study provides the basis for a better understanding of L1CAM regulation in non-neuronal/tumor cells." (PMID 20799950, 2010). "Of note, none of L1CAM expressing tumours in BHD-associated renal tumours and sporadic ChRCCs might arise from intercalated cells, suggesting that cell-of-origin may determine tumour characteristics of these tumours." (PMID 37182269, 2023).
tumor (continued). "Our findings verified that SELPLG knockout significantly improved L1CAM-CAR T cell migratory capacity in vitro, without altering anti-tumor function, and demonstrated that CAR T cells dynamically downregulate SELPLG surface expression during migration." (PMID 41394860, 2025). "Collectively, our data imply that overexpressing SH2D2A does not interfere with L1CAM-CAR T cell mechanisms used to recognize and kill tumor cells." (PMID 41394860, 2025). "Immunophenotypically, tumor cells usually express EMA, CK7, GATA3, and L1CAM, while CD117 and CAIX are negative." (PMID 37924117, 2023). "Immunohistochemistry and co-immunofluorescence show L1CAM expression in mature TLS, independent of L1CAM expression in the tumor." (PMID 35296668, 2022). "L1CAM positivity in ≥10% of cells in the MELF component, regardless of the overall expression in the whole tumor, appears as the strongest independent predictor of lymph node involvement in MELF cases." (PMID 35892892, 2022). "We unveiled L1CAM as a master regulator of OCSC pathophysiology through a previously unrecognized L1CAM/FGFR/SRC/STAT3 signaling pathway, thus shedding light on novel molecular mechanisms that sustain the tumor-supporting function of OCSC." (PMID 34645505, 2021). "Patients with L1CAM positive tumours who received adjuvant therapy showed longer DSS than the ones without adjuvant therapy (p=0.0055, L1CAM continuous; p=0.0426, L1CAM 10%)." (PMID 34659530, 2021). "In addition, interactions of L1CAM with growth factor receptors leading to receptor activation, is highly relevant for understanding cancer progression downstream of these receptors and has been studied in a much greater detail in non-cancerous cells as compared to tumor cells." (PMID 31455004, 2019). "Established GICs clearly display mesenchymal traits, greater clonogenic capacity, have greater self-renewal and tumorigenic capability, and express more L1CAM, CD44, CD133 and ITGA6 compared to the non-GIC tumor bulk cells." (PMID 29088733, 2017). "L1CAM expression in Mint3 KO MEFs increased the levels of Ki67, but not those of other markers, including CD31, in the tumour tissues." (PMID 28504692, 2017). "Taken together, our single-cell RNA expression analysis affirmed that SELPLG and SH2D2A are differentially regulated in single tumor-infiltrating L1CAM-CAR T cells, suggesting a functional role, while TIAM2, CORO1B and MYH10 do not seem to influence L1CAM-CAR T cell migration." (PMID 41394860, 2025). "For L1CAM knockdown, SKOV3 were preferred to OVCAR3 because the latter are tumorigenic only when injected at high number (our unpublished data) and, therefore, are not suitable for tumor initiation experiments." (PMID 34645505, 2021). "However, high background staining was observed in tumor-negative tissues for EGFR, VEGF-A and L1CAM." (PMID 32545676, 2020). "However, we could not reproduce the improved anti-tumor efficacy and survival in our immunodeficient NOG mouse model treated with human L1CAM-CAR T cells lacking functional SELPLG." (PMID 41394860, 2025).
cancer (226 papers, 2007 to 2025). A tumor composed of atypical neoplastic, often pleomorphic cells that invade other tissues. "In conclusion, our study linked L1CAM-dependent tumorigenesis and radioresistance, both hallmarks of cancer stemness, with phosphorylation of key proteins involved in DNA repair and mTORC1 signaling in HGSOC cells." (PMID 40429728, 2025). "It is also imperative to note that L1CAM has garnered attention in oncology, being implicated in the genesis and metastatic progression of diverse cancers." (PMID 39742488, 2025). "Although many of these studies have suggested associations between L1CAM expression and increased cancer aggressiveness, the available data on the prevalence of L1CAM expression are remarkably discrepant." (PMID 41328908, 2025). "The cancer cells expressed L1CAM (CD171) and EPCAM (CD326), which are prognostic/diagnostic biomarkers often overexpressed on cancer cells, with roles in supporting cell motility, invasion, proliferation, and metastatic progression." (PMID 41279931, 2025). "Another cancer stem cell or cancer initiating cell marker, L1CAM, is associated with poor prognosis in NSCLC and immunosuppression in pancreatic cancer." (PMID 38253555, 2024). "FOXC1 and L1CAM are known to be present in various types of cancer and have been implicated in cancer development based on in vitro experiments." (PMID 38183514, 2024). "Several genes, including ARRDC5, ELF5, FIBCD1, LINC00494, NLRP7, and L1CAM, have been implicated in various aspects of cancer progression and metastasis." (PMID 39697539, 2024). "As one of the neural adhesion molecules, L1CAM is expressed in many human cancers and is often associated with poor prognosis." (PMID 38049860, 2023). "Aberrant expression of L1CAM in different human cancers is often associated with poor survival prognosis." (PMID 37015905, 2023). "One potential blood marker for rHGP is SERPINF2 (alpha-2-antiplasmin), which inhibit plasmin and is associated with poor outcome in various cancer due to its role in preventing L1CAM destruction and promoting metastatic outgrowth during brain metastasis." (PMID 39516397, 2023). "Tail vein injection of MDA-MB-231-LM cells (lung metastatic subpopulation) also causes cancer cells to spread perivascularly in the lung, mediated by neural cell adhesion molecule L1 (L1CAM)." (PMID 36119528, 2022). "L1CAM is a highly glycosylated protein known to regulate cell attachment, invasion and migration in several cancers and is associated with poor prognosis." (PMID 36477196, 2022). "In pancreatic cancer, there is a strong association between L1CAM expression in cancer tissue and perineural invasion." (PMID 35223829, 2022). "Despite its initial discovery in the nervous system where it acts as a driver of neural development and plasticity, L1CAM is also aberrantly expressed in several solid tumors and was often associated with unfavorable prognosis in cancer patients." (PMID 34645505, 2021). "L1CAM, another cell surface protein strongly implicated in cancer progression and metastasis, demonstrated positive regulatory control by KDM5A and PHF2 in both cell lines." (PMID 33196691, 2020). "Previous studies have shown association of L1CAM with metastasis in cancer, thus the novel role as E-selectin counter-receptor contributes to understand the molecular mechanism involving L1CAM in metastasis formation." (PMID 33167483, 2020). "The L1 cellular adhesion molecule (L1CAM) has been implicated in the development of metastases in a wide range of malignant tumors." (PMID 33291528, 2020). "L1 cell adhesion molecule (L1CAM) is a glycoprotein involved in cancer development and is associated with metastases and poor prognosis." (PMID 31455004, 2019). "L1CAM, an axonal glycoprotein belonging to immunoglobulin superfamily, is associated with poor prognosis and metastases formation in several cancers, including breast and pancreas." (PMID 32047513, 2019).
cancer (continued). "Nevertheless, L1CAM can have a static function as a cell adhesion molecule and its expression is associated with good cancer prognosis." (PMID 31344926, 2019). "This would suggest that L1CAM expression is invariably implicated in cancer progression-related processes that highly negatively influence the course of the disease." (PMID 27832351, 2017). "Outside of neuronal tissue L1CAM expression was found to be associated with various human malignant tumors such as pancreatic tumors, colon cancer, melanoma, renal cell and endometrial carcinoma and was linked to a poor prognosis." (PMID 27174921, 2016). "The same study also analyzed the full length membrane bound form of L1CAM in cancer lysates, which correlated with an increased risk of residual disease after debulking and was higher in type-II carcinomas." (PMID 27174921, 2016). "As the most consistent outcome throughout the various studies is the association of L1CAM positivity with distant relapse, it appears reasonable that patients with L1CAM positive cancers are candidates for a systemic adjuvant chemotherapy." (PMID 27233077, 2016). "High expression of L1 cell adhesion molecules (L1CAM) has been repeatedly shown to be associated with aggressive disease behavior, which translates in poor clinical outcome in various cancer entities." (PMID 27174921, 2016). "The expression of L1CAM, an adhesion molecule, is associated with poor prognosis and spontaneous metastasis of cancer cells to the lung." (PMID 27285767, 2016). "Of special note is that L1CAM mRNA expression was found to be significantly higher in intermediate-high risk (median value 0.02; Q1-Q3: 0.01-0.08) as compared to low risk cancers (median value: 0.01; Q1-Q3: 0.01-0.02; p=0.003)." (PMID 27233077, 2016). "Expression of the L1 cell adhesion molecule (L1CAM) frequently occurs in human cancers and is associated with poor prognosis in cancers." (PMID 26116372, 2015). "Numerous studies have demonstrated the distinction of L1CAM's presence in cancerous vs. normal tissues in various cancer types, which is also associated with cancer progression." (PMID 25294816, 2014). "ix) Finally, localization of CD68+ (H2) and CD163+ (I2) macrophages close to carcinoma cells as well as high expression of FoxP3 (O2), L1CAM (P3) and vimentin (R), respectively, tended to be associated with higher grading (S)." (PMID 24797069, 2014). "Future studies will reveal the utility of SSEA-5 and L1CAM in diagnostic and therapeutic strategies in both cancer biology and regenerative medicine." (PMID 26317026, 2013). "L1CAM (CD171), a glycoprotein encoded by a gene located on the X chromosome, is part of the family of neural adhesion molecules and has been studied in relation to novel cancer antigens." (PMID 39489087, 2024). "L1CAM is a newly and important cancer-associated gene in several malignant tumors." (PMID 33710805, 2021). "As outlined in Section 4.1, L1CAM is causally related to chemoresistance in various cancer types, which suggests that interfering with L1CAM function may enhance the response to other treatments." (PMID 32429448, 2020). "The L1 cell adhesion molecule (L1CAM), a cell surface glycoprotein previously implicated in the development and plasticity of the nervous system, is aberrantly expressed in the vasculature of various cancer types." (PMID 28134764, 2017). "Furthermore, it should be considered that cancers rated high risk by multifactor assessment, known to have a higher likelihood to be L1CAM positive, are overrepresented with 73 % in this cohort." (PMID 27233077, 2016). "In addition, high L1CAM expression was associated with the progression of many other human cancers, including triple negative breast cancer, non-small lung cancer, pancreatic ductal adenocarcinoma, renal cell carcinoma, melanoma and glioblastoma." (PMID 27833079, 2016).
cancer (continued). "Moreover, L1CAM has been linked to EMT (epithelial to mesenchymal transition) in several different cancer types, including ECs." (PMID 27233077, 2016). "Although a majority of studies have shown that high L1CAM expression is interrelated with poor prognosis, the association between L1CAM overexpression and the outcome of cancer patients remains unknown." (PMID 27833079, 2016). "p38 mitogen-activated protein kinase (MAPK) and ERK have been implicated in cancer metastasis signaling pathways and may be involved in regulating L1CAM activation." (PMID 24660028, 2014). "In many human carcinomas L1CAM is over-expressed and is associated with a bad prognosis." (PMID 23530769, 2013). "L1CAM positive carcinomas are associated with bad prognosis." (PMID 20799950, 2010). "Besides, the high frequency of L1CAM expression in high‐risk ECs indicates a potential role as a therapeutic target against which human monoclonal antibody (MAb) approaches have been explored in various types of cancer." (PMID 35429348, 2022). "However, only a few sporadic reports have implicated L1CAM in cancer stem cells (CSC)." (PMID 34645505, 2021). "Indeed, interfering with the function of cell surface-associated endothelial L1CAM and, at the same time, with that of extracellular L1-ΔTM might result in efficient repression of cancer angiogenesis." (PMID 30829570, 2019). "There are several hypotheses regarding the underlying mechanism of L1CAM upregulation in cancer." (PMID 27028855, 2016). "L1CAM knockout resulted in a 2.3-fold reduction in the cancer stem cell (CSC) frequency, which was sufficient to significantly decrease the tumorigenicity." (PMID 40429728, 2025). "Cancer-cell factors also condition the nerve microenvironment: the L1 cell adhesion molecule (L1CAM) on PDAC cells induces MMP-2 and MMP-9 via STAT3 signaling, promoting nerve infiltration; L1CAM blockade reduces PNI in mouse models." (PMID 41394398, 2025). "In conclusion, our study established a link between L1CAM-dependent tumorigenesis and radioresistance, both hallmarks of cancer stemness, with phosphorylation of key proteins involved in DNA damage response." (PMID 40429728, 2025). "L1CAM is expressed in tumors, promoting cancer aggressiveness and resistance to treatment and serving as an indicator of poor prognosis." (PMID 40699746, 2025). "L1 cell adhesion molecule (L1CAM), secreted by Schwann cells, acts as a potent chemoattractant for cancer cells, promoting neural invasion via the activation of MAP kinase signaling and upregulation of matrix metalloproteinases (MMP‐2 and MMP‐9)." (PMID 40981722, 2025). "Eventually, the potential use of L1CAM as a biomarker for cancer diagnosis and prognosis was found to be prominent, since L1CAM identifies cells that initiate metastasis with stem cell-like features and resistant traits towards chemotherapy." (PMID 40699746, 2025). "The research delves into how silencing L1CAM impacts cancer cells, specifically focusing on the Capan-2 cell line." (PMID 40699746, 2025). "In TNBC, FOXC1 can co-regulate with L1 cell adhesion molecule (L1CAM) to promote cancer cell invasion, motility, and lung metastasis." (PMID 40822238, 2025). "Other L1CAM-influenced cellular processes such as RNA processing, splicing and the RHO GTPase cycle have also been associated with malignant transformation cancer stemness and radioresistance." (PMID 40429728, 2025). "Distinct adhesion molecules expressed by cancer cells, including β1 integrin, α6 integrin and the axonal path-finding neural cell adhesion molecule L1 (L1CAM), have been shown to facilitate this attachment to vessels." (PMID 39940673, 2025). "Targeting L1CAM protein in cancer cells is currently being evaluated by various approaches, including neutralizing antibodies, bispecific antibodies, radioimmunoconjugates and chimeric antigen receptor-redirected T (CAR-T) cells." (PMID 41328908, 2025).